IL1B (interleukin 1 beta)
Diseases named in the same sentence as IL1B in open-access papers (continued):
Sharing a sentence is not in itself a finding about the gene and the disease.
melanoma (continued). "In an autocrine manner, tumor-derived IL-1β stimulated melanoma cell proliferation." (PMID 29983861, 2018). "Thus, pharmacologically inhibiting CXCR2 signaling represents an attractive therapeutic approach that would prevent IL-1β–activated fibroblasts from protecting melanoma cells from MAPK inhibition." (PMID 28450382, 2017). "The increase in macrophage abundance and IL1B expression on treatment could contribute to the adaptive response of melanoma cells that promotes treatment tolerance." (PMID 28450382, 2017). "The role of IL-1β in cancer invasion was clarified in B16 murine melanoma models." (PMID 28360909, 2017). "The level of IL-1β is correlated with metastasis potential of melanoma." (PMID 28360909, 2017). "Interestingly, there was no tumor formed in Il1b knockout group, which highlighted the important role of IL-1 especially IL-1β in carcinogenesis and cancer invasion of B16 melanoma." (PMID 28360909, 2017). "Interestingly, although ordinarily undetectable, we observed IL-1β precursor protein expression in melanoma cells infected with mycoplasma (unpublished data)." (PMID 28450382, 2017). "In primary melanoma, the secretion of IL-1β needs abundant external stimuli." (PMID 28360909, 2017). "However, we demonstrate that, when activated by IL-1β, fibroblasts can protect melanoma cells from MEK inhibition through an ERK-independent mechanism." (PMID 28450382, 2017). "However, in other types of cancer, such as melanoma and mesothelioma, inflammasomes and IL-1β have been shown to enhance tumor growth." (PMID 27786298, 2016). "IL-1α and IL-1β transcript levels have been evaluated in melanoma, non-small cell carcinoma, colon, and squamous cell cancer cell lines via real-time qRT-PCR, and several of these cell lines exhibit significantly increased levels of IL-1α or IL-1β." (PMID 26176534, 2015). "In addition, IL-1β can directly act on melanoma cells to promote their survival, proliferation, adhesion and colony formation." (PMID 25706411, 2015). "First, B16F10 melanoma cells (at 6×104) were injected into the femoral vein of mice, and formation of lung nodules, levels of lung IL-1β and serum cytokines, and accumulation of myeloid-derived suppressor cells (MDSCs) were compared between WT and DJ-1 KO mice." (PMID 25706411, 2015). "IL-1β mRNA expression is primarily found in myeloid cells, although it is also expressed by other cell types and its expression is enhanced in a number of cancers including lung, colon, melanoma, and breast." (PMID 26378020, 2015). "Furthermore, melanoma cells secrete large amounts of pro-inflammatory cytokines, including interleukin (IL)-8, IL-1β, and IL-6, and growth-related oncogene (GRO)-α which also facilitate breakdown of endothelial cell-cell junctions." (PMID 25225982, 2014). "In addition, an unexpected inducer of VEGF-C expression in human melanoma cells was the low extracellular pH, which has been demonstrated to enhance IL-1β production by monocytes." (PMID 25120672, 2014). "In this study, we examined the roles of the melanoma cell inputs, IL-8, IL-1β, and VCAM-1 activation, and the endothelial cell outputs, actinomyosin contraction, junction disassembly, and actin remodeling, in melanoma-induced endothelial cell-cell junction breakdown." (PMID 25225982, 2014). "While IL-1β is not generally considered to be a cytokine which mediates cytotoxic activity, a previous study found that IL-1β had a direct cytotoxic effect on tumor cells, with human monocyte-derived IL-1β found to be growth-inhibitory and cytocidal in A375 melanoma cells." (PMID 25120672, 2014). "Turning on all three inputs, VCAM-1, IL-8, and IL-1β, represented the melanoma cell stimulus." (PMID 25225982, 2014). "Additionally, the angiogenic effects of IL-1 observed in the wild-type model were restored when IL-1β KO mice received plug implants containing melanoma cells with IL-1α." (PMID 17096856, 2006).
melanoma (continued). "Interestingly, IL-1β is transcriptionally induced to support vemurafenib resistance in melanoma." (PMID 41145465, 2025). "Therefore, we next analysed whether the enhanced melanoma cell intercalation into IL-1β-stimulated pMBMECs is only the result of enhanced adhesion or is additionally enhanced." (PMID 37894438, 2023). "Therefore, we questioned whether melanoma cells could become the dominant source of TNF-α in the skin or whether indirect activation of KCs in tumor-bearing skin, for example, via melanoma IL-1β, would also contribute to TNF-α–dependent migration of LCs." (PMID 37043573, 2023). "Therefore, we might argue that interruption of IL-1β signaling in patients with melanoma might negatively impact the disease progression." (PMID 36611037, 2023). "However, the intercalation of melanoma cells into the junction-compromised Il-1β-stimulated pMBMECs was stronger than the upregulation of VCAM-1 and thus may be a consequence of the weakened junctions of the pMBMECs." (PMID 37894438, 2023). "Moreover, IL-1β secretion becomes autonomous as melanoma is progressing." (PMID 35334544, 2022). "Thus, we sought to assess whether tumor-derived IL-1β induces the IL-6/STAT3 signaling axis in melanoma cells." (PMID 34531850, 2021). "We have previously shown that a cytokine cocktail consisting of IL‐1β, TNFα, IFNγ, IFNα, and Poly I:C can yield stable, type‐1 polarized DC that produce up to 100‐fold higher levels of IL‐12p70 and can induce very high levels of melanoma‐specific CTLs as compared to standard DCs." (PMID 32663904, 2021). "However, different authors have consistently maintained that EDPs induced the production and/or secretion of IL-1α, IL-1β, and IL-6 in ligamentum flavum cells, synovial cells, and melanoma cell lines; therefore, we can assume that caspase-1 should be activated by EDPs in these cells." (PMID 31691186, 2020). "However, despite upregulated MGMT expression, the resistant mechanism was independent of MGMT, and the cells that acquired TMZ resistance showed increased NLRP1 inflammasome activation, NF-κB activity, and IL-1β secretion, which contributed to the melanoma cells’ resistance to TMZ." (PMID 32899791, 2020). "As both melanoma cells and macrophages exposed to supernatants from bcl-2-overexpressing cells expressed higher levels of the receptors for IL-1β, IL-17, IL-8 and CCL2, it is conceivable that these cytokines may critically support an active interplay between the tumoral and stromal compartments." (PMID 32269145, 2020). "Moreover, in a model of melanoma, myeloid cells was shown to produce IL-1β, which subsequently activated endothelial cells to produce VEGF and other proangiogenic factors, modulating the inflammatory microenvironment of the tumor, allowing for enhanced angiogenesis and tumor progression." (PMID 31231372, 2019). "In addition, recombinant IL-1β increased the number of invading melanoma cancer cells." (PMID 31439870, 2019). "Furthermore, BRAFi treatment-induced tolerance in melanoma could be shown to result from a cytokine-signaling network involving TAM-derived IL-1β and CAFs derived C-X-C motif chemokine receptor 2 (CXCR2) ligands." (PMID 30042333, 2018). "Therefore, it is conceivable that IL-1β secreted from immune and melanoma cells in the tumor inflammatory microenvironment contributes to progression of cancer, including angiogenesis, invasion, and metastasis, via COX-2 expression and subsequent prostaglandin E2 production and release." (PMID 30562372, 2018). "Moreover, the production of IL-1β by melanoma cells could be inhibited by the caspase-1 inhibitor or IL-1R blockade." (PMID 28955343, 2017). "Thus, melanoma tumors appear to contain IL-1β–signaling inflammatory niches, a configuration where cross talk between macrophages and stromal cells may be optimized." (PMID 28450382, 2017). "Moreover, the secretion of IL-1β is also phase-dependent in melanoma." (PMID 28360909, 2017).
melanoma (continued). "This screening has shown that concentrations of 15 biomarker proteins (IL-1α, IL-1β, IL-6, IL-8, IL-12p40, IL-13, G-CSF, MCP-1, MIP-1α, MIP-1β, IFN-α, TNF-α, EGF, VEGF, and TNF-RII) were significantly higher in patients with resected high-risk melanoma compared with healthy controls." (PMID 28050120, 2016). "To explore how LINC01198 influences IL1B expression, we first determined the subcellular localization of LINC01198 in vemurafenib-resistant melanoma cells by fluorescent in situ hybridization (FISH) and nuclear-cytoplasmic fractionation." (PMID 41145465, 2025). "explored the connection between the inflammasome sensor NLRP1 and acquired drug resistance to temozolomide in melanoma, as NACHT, LRR, and PYD domains‐containing protein inflammasomes play a role in IL‐1β maturation and NF‐κB activation." (PMID 40237399, 2025). "The roles of IL-1A and IL-1B have been extensively studied in various cancers, including non-small-cell lung cancer (NSCLC), head and neck squamous cell carcinoma, melanoma, colorectal adenocarcinoma, glioma, and cervical cancer." (PMID 41465261, 2025). "In melanoma patients unresponsive to vemurafenib treatments, both LINC01198 and IL1B were significantly upregulated compared to patients sensitive to vemurafenib treatments." (PMID 41145465, 2025). "Intriguingly, while CXCL2 was expressed by fibroblasts from all skin cancer types, melanoma-derived CAFs expressed high levels of CXCL1-3, 5, 6 and 8 and IL1B as well as IL6, whereas the expression of CXCL9-11 and 13 was high in non-melanoma CAFs." (PMID 39516494, 2024). "Increased levels of various cytokines and growth factors, including IL-6, GM-CSF, VEGF, IL-1β, and IFN-γ, were described in melanoma lesions of Ret transgenic mice." (PMID 39126091, 2024). "IL-1β stimulated IL-8 and GROα production in fibroblasts, both of which further induced resistance to MAKP inhibition in melanoma cells." (PMID 38303024, 2024). "Further, it has been shown that pro-inflammatory cytokines and chemokines like IL-1β, IL-6, MCP-1, and TNF-α also play a major role in the inflammation-mediated pathogenesis of melanoma." (PMID 39769450, 2024). "Meanwhile, increased pro‐inflammatory factors, including IL‐1β, TNF‐α, IFN‐α, and IFN‐β, were also presented in macrophages co‐cultured with irradiated melanoma cells." (PMID 38286661, 2024). "For example, serum IL-1β, IL-4, IL-6, IL-10, GM-CSF, TNF-α, and sPD-L1 has significant sex-related predictive effects on OS in patients with melanoma or non-small cell lung cancer treated with ICIs." (PMID 39085893, 2024). "IL-1β and IL-18 enhance the expression of adhesion molecules, like VCAM-1, facilitating melanoma cell attachment to blood vessel walls and promoting their migration to other organs." (PMID 39329914, 2024). "Serum IL-1β, IL-4, IL-6, IL-10, GM-CSF, TNF-ɑ, and sPD-L1 had a significant sex-related predictive impact on ORR, PFS and OS in melanoma and NSCLC patients treated with ICIs." (PMID 38443899, 2024). "As up-regulated genes (IL-8, IL-1β, MCSF and CCL5) in Bcl-xL overexpressing melanoma cells have in common that are all regulated by NF-κB, we evaluated if this transcription factor was the intermediary between Bcl-xL and the release of these cytokines." (PMID 37488586, 2023). "Expression of Tnf, Il1b, Pros1, and Gas6 was enhanced upon tumor growth in vivo, as was Dkk1, in contrast to studies showing down-regulation of DKK genes in melanoma cell lines in vitro, relative to melanocytes." (PMID 37043573, 2023). "Nevertheless, melanoma expresses high NLRP3-derived IL-1β expression, which specifically induces pSTAT3 and amplifies IL-6 secretion through the IL-1β/IL-6/STAT3 axis in vivo, leading to a further expansion of MDSCs." (PMID 36911674, 2023). "Recent studies have revealed that IL7 plays a significant role in glioma, melanoma and leukemia by contributing to anti-tumor effects through the release of cytokines, including IFNG, IL1A, IL1B, TNF, IL2 and IL4." (PMID 37958451, 2023).
melanoma (continued). "Because IL-1β is secreted via various pathways, TQ as an inhibitor to NFκB and NLRP3 in melanoma was an excellent candidate to lessen its expression in the current study." (PMID 37762557, 2023). "In the present study, we demonstrated that IL-1β triggers MMP-3 expression and release in canine melanoma cells." (PMID 36445856, 2022). "While we provided evidence that melanoma cells can produce both TGF-β and IL-1β, IL-33 was undetectable in supernatants from both A375 and RPMI-5971 cells." (PMID 35669782, 2022). "Robust generation of mitochondrial superoxide and production of IL-1β induced by Treg-specific ablation of GPX4 help to potentiate antitumor immunity and repress tumor growth in melanoma." (PMID 36003368, 2022). "Overall, these findings show that the administration of a combination of PTS and cisplatin strongly inhibited the expression of the inflammatory cytokines IL-1β, TNF-α, and IL-6 in canine melanoma." (PMID 36077992, 2022). "In melanoma cells, ABCB5 controls IL-1β/IL-8 signaling which, in turn, influences chemoresistance by activating Smad/DNA binding protein 1 signaling." (PMID 35530309, 2022). "UVB-induced melanogenesis is mediated in part by IL-1β, leading to upregulation of the TYR/TRP1 expression in melanoma B16 cells." (PMID 35572734, 2022). "Taken together, melanoma cells secreted a variety of proinflammatory factors, mainly cytokines, such as IL-1β and IL-8, and chemokines, such as CXCL10, CXCL11, and CCL20, during CIS, while during TIS, melanoma cells produced lower levels of SASP proteins." (PMID 35563820, 2022). "In our study, an MMP-3 inhibitor significantly inhibited IL-1β-mediated melanoma cell migration, supporting the role of MMP-3 in melanoma metastasis." (PMID 36445856, 2022). "The relative expression level of the hub genes was reverified in melanoma cell lines, and showed that HIF1A, IL1B, HMOX1, MMP3, CDKN2A and TIMP1 were upregulated, while PTEN, PRKCA, ATF3 and BRAF were downregulated in melanoma samples." (PMID 36226170, 2022). "Autophagy secreted proteins, such as IL‐1β, CXCL8, LIF, are shown to be elevated in high‐autophagy melanoma cell lines." (PMID 36124714, 2022). "Melanoma involves upregulation of pro-inflammatory cytokines, such as IL-6, IL-8, C-C chemokine ligand 5 (CCL5), and IL-1β, along with VEGF." (PMID 35334544, 2022). "The lower melanoma pH is responsible for decreased cytolytic activity of CD8+ T cells and increased secretion of IL-1β by monocytes and TAMs, as well as a functional orientation of TAMs toward the M2 type." (PMID 35334544, 2022). "In vitro, we show that melanoma cell supernatants and tumor microenvironment (TME) mediators such as TGF-β, IL-33, and IL-1β induce some of the changes found in MAMCs and significantly modulate C3 expression and activity in MCs." (PMID 35669782, 2022). "The mRNA expression level of inflammatory cytokines such as IL-1β, IL-6, and TNF-α confirmed the macrophage activation state upon the treatment with the acid EV derived from all the three melanoma cell lines used." (PMID 36291876, 2022). "In our study, treatment with the IκB kinase inhibitor TPCA-1 resulted in the inhibition of IL-1β-induced MMP-3 mRNA expression and protein release in melanoma cells." (PMID 36445856, 2022). "Using cancer databases, we found higher expression of NLRP3 in skin biopsies of melanoma lesions compared to normal skin and with NLRP3 expression positively correlated with expression of IL-1β." (PMID 33649199, 2021). "Using a mouse model of melanoma, we report here that NLRP3 activation induces IL‐1β-mediated IL‐6 production resulting in STAT3 activation." (PMID 34531850, 2021). "CD37 inhibition suppresses lung metastasis originating from melanoma through the induction of expansion of CD11b+Gr-1hi myeloid cells and enhancing the synthesis of TNF-α and interleukin 1β (IL-1β)." (PMID 32902664, 2021).
melanoma (continued). "Studies using a melanoma brain metastasis immunocompetent mouse model revealed an upregulation in proinflammatory cytokines CXCL10, CCL17, CCL2, IL6, and IL-1β." (PMID 33466236, 2021). "The most aggressive form of skin cancer is melanoma which is characterized by upregulation of several pro-inflammatory cytokines, including IL-6, IL-8, CCL5, and IL-1β, the expression of which can be regulated by IL-1β5,64,66." (PMID 33686176, 2021). "Specifically, the addition of anti-HMGB1 significantly reduced the expression of iNOS and IL-1β secretion in WEHI-3 and RAW 264.7 cells co-cultured with Salmonella pre-treated melanoma cells." (PMID 34207850, 2021). "Measurements included LDH, interleukin (IL)-6, IL-1β, IL-17, C-reactive protein (CRP) and tumor necrosis factor (TNF)-alpha as well as tumor markers S100 and melanoma inhibitory activity (MIA)." (PMID 33837821, 2021). "Immunohistochemistry of stage III melanomas showed that 75% of the 51 cases had strong expression of JNK, 20% had positive expression of pJNK, and all pJNK-positive tumors were IL-1β-positive." (PMID 32252279, 2020). "Accordingly, our data revealed that enhanced concentrations of IL-1β in HNSCC and melanoma patients were positively correlated with advanced tumor stage." (PMID 32547321, 2020). "The mechanism behind the autocrine production of IL-1β of melanoma cells is that NACHT, LRR, and PYD domains-containing protein (NLRP) inflammasomes, the cellular machinery responsible for IL-1β maturation, are constitutively activated." (PMID 33396632, 2020). "In vitro, human samples (metastatic melanoma) and human cell lines (melanoma, oral squamous cell carcinoma (OSCC)) have been shown to produce IL-1β, which favors tube formation by HUVEC cells." (PMID 32635472, 2020). "Similar enrichments were observed for experimental gene sets of IL-1β-, TNFα-, or TGF-β1-response induced in human melanoma cell lines, primary endothelial cells, fibroblasts, melanocytes, or CD4+ T cell clones." (PMID 32917858, 2020). "The effect and mechanisms of IL-1β on tumor cell growth, migration, invasion and stemness characters were studied using HNSCC cell SCC7 and melanoma cell B16-F10." (PMID 32547321, 2020). "Because NACHT, LRR and PYD domains-containing protein (NLRP) inflammasomes mediate IL-1β maturation and NF-κB activation, we investigated the role of inflammasome sensor NLRP1 in acquired drug resistance to temozolomide (TMZ) in melanoma." (PMID 32899791, 2020). "In melanoma, the NLRP3 inflammasome components, CASP-1, IL-1β, and IL-18, are involved in tumorigenesis and metastasis formation." (PMID 33014808, 2020). "Serum expression of IL-1b, IL-6, IP-10, PDGF-BB, and RANTES was found to be significantly different in melanoma vs. controls, reinforced by a much larger patient cohort, since previous observations were carried out on much smaller patient cohorts." (PMID 33302400, 2020). "Melanoma cells exhibit a high activation level of the IL-1 β/COX-1 axis, which leads to the upregulation of tumor-promoting factors (i.e., IL-1β, IL-8, and VEGF) expression by macrophages, as well as their phenotype switch toward the M2 type." (PMID 33171792, 2020). "In melanoma, production of VEGF and other proangiogenic factors by endothelial cells is dependent on myeloid cell (macrophages or MDSCs)-derived IL-1β." (PMID 32635472, 2020). "Studies of molecular mechanisms have shown that IL-1β promotes the stemness of HNSCC and melanoma cells, through the activation of Smad/ID1 signalling pathways and the upregulation of stemness factor genes (Bmi1 and Nestin), thus increasing drug resistance." (PMID 32825489, 2020). "The tumor microenvironment of melanoma is shaped by the level of MITF expression and depletion of MITF stimulates the release of inflammatory cytokines such as IL-6 and IL-1β." (PMID 33293474, 2020).